CD4 (CD4 molecule)
Diseases named in the same sentence as CD4 in open-access papers (continued):
Sharing a sentence is not in itself a finding about the gene and the disease.
metabolic disease (38 papers, 2013 to 2025). A congenital disorder (due to inherited enzyme abnormality) or acquired (due to failure of a metabolically important organ) disorder resulting from an abnormal metabolic process. "Tm with CD4+ are a very significant cell subset that play a crucial role in a range of disorders, such as graft‐versus‐host disease, malignancies, metabolic diseases, and pathogenic infections, as well as in vaccinations." (PMID 37647444, 2023). "While ART is vital for viral suppression, it introduces challenges such as mitochondrial toxicity, metabolic disorders, and decreased CD4 cell counts, accelerating the aging process." (PMID 40255985, 2025). "In other words, the CD4+ T cells in adult patients with HF suffer from metabolic disorders of zinc and copper ions." (PMID 37705737, 2023). "CD4+ T cells were isolated from peripheral blood of dairy cows diagnosed as healthy or with ketosis, a common metabolic disorder of FA metabolism." (PMID 35663942, 2022). "T cells are involved in the inflammatory response, which can also regulate the development of metabolic diseases, CD4+ T cells and CD8+ T cells are mainly responsible for the role." (PMID 36428983, 2022). "LSM >12.5 kPa at any time remained associated with an increased risk of liver-related mortality (aHR = 20.60 [5.99–70.78], p<0,001) after adjustment for sex, alcohol use, metabolic disorders, CD4+ level and previous HCV treatment." (PMID 30682180, 2019). "In the LSM >12.5 kPa group, patients were older, mostly men, had lower CD4+ counts, had more frequent metabolic disorders, were more often under HCV treatment at inclusion, and were more often pretreated for HCV." (PMID 30682180, 2019). "Thus, the upregulation of LC3 in ketotic cows or fatty acid-challenged CD4+ T cells underscored the value of this protein as a biomarker autophagosome formation in the context of metabolic disease." (PMID 35663942, 2022). "The outcomes of our study showed that the reduction of MAIT cells and increased frequency of CD4+MAIT cells may contribute to the metabolic disorder and follicular development in PCOS." (PMID 36518256, 2022). "The outcomes of our research gave a clue that the combined reduction of CD8+MAIT cells and MDSCs, and increased population of CD4+MAIT cells might contribute to the metabolic disorders in PCOS." (PMID 34847942, 2021). "Given that the gut microbiota regulates intestinal CD4-positive T cells to control metabolic diseases, the HFD-induced colonic macrophage activation may be the secondary effects caused by the T cell pyroptosis and its-related gut dysbiosis." (PMID 34275417, 2021). "Specifically, the enrichment of memory CD4+ T cells in both blood and adipose tissue of MUO individuals underscores their immunological contribution to metabolic disease." (PMID 40244276, 2025). "Our group and others have previously shown CD4+ and CD8+ tissue-resident T cells accumulate with metabolic disease in PWH." (PMID 37711619, 2023). "The activation of MTOR regulates various effector functions of CD4+ and CD8+ T cells, and MTOR inhibitors (i.e., rapamycin) are used as potential immunosuppressive therapeutics for organ transplants, metabolic diseases, and various autoimmune disorders." (PMID 30469437, 2018). "In this study we observed that selenium supplementation has beneficial effects on body composition and on CD4+ T cell replenishment in PLWHIV on long-term ART without metabolic diseases." (PMID 39351495, 2024). "Thus, the aim of this study was to assess the effect of zinc and selenium supplementation on body composition, bone mineral density, CD4+ T cell replenishment, lipid profile, glucose levels and immune system status in PLWHIV on ART without metabolic diseases." (PMID 39351495, 2024).
metabolic disease (continued). "Second, our study did not include matched controls without HIV and with metabolic diseases (non-diabetic, pre-diabetic, and diabetic), which would be necessary to understand whether CGC+ CD4+ T cells demonstrate a similar role in HIV-negative individuals." (PMID 36865544, 2023).
heart disease (29 papers, 2010 to 2025). "A higher proportion of Th1, senescent and/or exhausted T cells, and a lower frequency of circulating multifunctional CD4+ T subset in CCC patients have been associated with the progression of heart disease." (PMID 38726014, 2024). "While recent interest in the role of CD4+ helper T cells and their subpopulations has uncovered both detrimental and beneficial effects in heart disease, less is known about the role of cytotoxic CD8+ T cells after ischemic injury in the heart." (PMID 33297741, 2021). "Our data presented here suggest a differential modulation of the expression of IL-27R between CD4+ and CD8+ T cells in the memory T-cell compartment during T. cruzi infection in vitro and ex vivo, which was associated with a milder cardiac disease." (PMID 34061845, 2021). "CD4+ T cell activation not only plays an important role in cardiac remodeling, but also facilitates the development of non-heart diseases, e.g., human immunodeficiency virus infection." (PMID 32327611, 2020). "IFN‐γ secretion in T cells decreased with the severity of cardiac disease in both 24 CD4+ 7 and CD8+ 37 T cell subsets." (PMID 28967229, 2018). "In this study, we report for the first time AT2R expression on CD4+ T cells in human as well as in rat, and describe its regulation in cardiac disease." (PMID 25991381, 2015). "Polyclonal stimulation with anti-CD3 antibodies induced higher frequencies of CD4+CTAL-4+ T cells in patients with severe heart disease than in asymptomatic subjects." (PMID 22574131, 2012). "In agreement with this notion, we have previously reported that naïve CD4+ T cells are diminished during the chronic phase of T. cruzi infection, particularly in patients with mild or severe heart disease." (PMID 22574131, 2012). "Therefore, we tested the subtypes of Th1 (CD4+IFNγ+), Th2 (CD4+IL4+), and Treg (CD4+CD25+Foxp3+) cells, which influence inflammation associated with heart disease." (PMID 31547872, 2019). "However, non-IFN-γ synthesizers had lower STAT-5 phosphorylation, less IL-7 receptor functionality, and reduced CD25 regulation (mainly in those with severe heart disease) in CD4+ T cells, accompanied by lower Bcl-2 expression in TCD4+ and TCD8+ cells after IL-7 stimulation." (PMID 39907396, 2025). "Subjects with severe chagasic heart disease also display an increased frequency of fully differentiated total CD4+ and CD8+ T cells and high rates of T cell apoptosis, leading us to propose that long-term parasite persistence might drive the immune system to exhaustion." (PMID 22574131, 2012). "Trypanosoma cruzi-infected subjects without heart disease (i.e., G0 clinical group) also showed an increased frequency of CD4+ and CD8+ T cells while expressing pSTAT3 or pSTAT5, but not pSTAT1, in response to IL-27." (PMID 34061845, 2021). "Interestingly, the same study demonstrated that the fraction of antigen‐specific T cells measured by surface CD4+/CD154+ and intracellular CD4+/TNF‐α+ T cells was almost undetectable in chronic adult chagasic patients with mild cardiac disease." (PMID 28967229, 2018). "As a whole, T. cruzi induced downregulation and upregulation of IL-27R in CD4+ and CD8+ T cells, respectively, in subjects with or without mild cardiac disease, while IL-27R remained unaltered in patients with severe disease." (PMID 34061845, 2021). "T. cruzi induced a downregulation of the expression of the IL-27R in CD4+ T cells along with an upregulation in CD8+ T cells of uninfected subjects and chronic Chagas disease patients with no signs of heart disease (i.e., the G0 group)." (PMID 34061845, 2021). "In vitro exposure of PBMCs to T. cruzi induced a downregulation of IL-27R in CD4+ T cells and an upregulation in CD8+ T cells in subjects without heart disease, while IL-27R expression remained unaltered in subjects with more severe clinical stages." (PMID 34061845, 2021).
heart disease (continued). "IFN-γ nonproducers with cardiac disease (i.e., subjects of the G1, G2 and G3 clinical groups) exhibited lower frequencies of phosphorylated STAT5+ (pSTAT5) in CD4+ T cells than IFN-γ producers and uninfected subjects, in response to IL-7." (PMID 30517089, 2018). "IFN-γ producers in patients with cardiac disease (i.e., subjects in the G1, G2 and G3 clinical groups) exhibited lower frequencies of RTE in the CD4+ and CD8+ T-cell compartments compared with IFN-γ nonproducers and uninfected subjects." (PMID 30517089, 2018).
liver (26 papers, 2012 to 2025). "Previous research posits that the abundance of peripheral CD4+ T cells may prognosticate outcomes in patients afflicted with gastrointestinal tumors and is closely associated with the efficacy of immunotherapy." (PMID 37960219, 2023). "In conclusion, we report previously unrecognized pro-tumorigenic roles for G-CSF in gastrointestinal tumors through inhibition of CD4+ and CD8+ T cell responses by promoting IL-10 and reducing cytotoxic responses in IFNγ- and IL-17A- dependent mechanisms." (PMID 33042110, 2020). "In summary, we report here previously unrecognized pro-tumorigenic roles for G-CSF in gastrointestinal tumors through inhibiting CD4+ and CD8+ T cell responses by promoting IL-10 secretion and reducing cytotoxic responses." (PMID 33042110, 2020). "Administration of anti-granulocyte colony-stimulating factor antibodies suppressed the colon carcinogenesis and significantly increased the levels of NK cells and IFNγ-producing CD4+ and CD8+ T cells." (PMID 28861089, 2017). "In summary, the high expression of T‐cell‐related molecular markers CD3, CD4, CD8, CD45RO, B‐cell‐related molecular marker CD20, DC‐related molecular marker CD103, and B‐cell and DC‐related molecular marker CD11c is significantly correlated with TLS and gastrointestinal tumors." (PMID 39259184, 2024). "Interestingly, elevated expression of the CD4 T cell antigen presentation molecule, HLA-DR, was noted to be an independent favourable prognostic indicator in OAC and other gastrointestinal tumour types, further highlighting the importance of CD4 T cells involvement in antitumour responses." (PMID 32582553, 2020). "Peritoneal cavity-derived B cells, although naturally enriched for IL-10-producing cells, were solely able to ameliorate, but not to prevent, T cell-induced colon inflammation when transferred to Rag−/− recipients along with colitogenic CD4+CD25−CD45RBhi T cells." (PMID 27353032, 2016).
respiratory disease (26 papers, 2014 to 2025). "In some animal models of respiratory virus infection, a Th2-type CD4+ T-cell response has caused vaccine-associated enhanced respiratory disease." (PMID 39131158, 2024). "The induced Th2-biased CD4+ T cells in mice and hamsters reportedly lead to vaccine-associated enhanced respiratory disease (VAERD) upon SARS-CoV-2 infection." (PMID 38409262, 2024). "The CD4 Th2 phenotype has been associated with vaccine-associated enhanced respiratory disease (VAERD) in those vaccinated against measles virus and respiratory syncytial virus." (PMID 35803578, 2022). "Previously, the CD4 TH2 phenotype has been associated with vaccine-associated enhanced respiratory disease (VAERD) in patients vaccinated against rubella, respiratory syncytial virus, and in preclinical studies of potential SARS and MERS vaccines." (PMID 33547083, 2021). "Polarization of CD4 T cells to a Th2 profile might potentially be detrimental, as they have been linked to vaccine-associated enhanced respiratory disease." (PMID 34671348, 2021). "We found that T CD4+/IL-4+ and T CD4+/IL-10+ populations were highly increased in the RS group, and our results are consistent with these reports, suggesting that chronic stress might be promoting lung susceptibility to infectious and respiratory diseases." (PMID 41155294, 2025). "For the current work, we confirmed some of the pros of using the RBD such as induction of the Th1 response, which was reported with several vaccine platforms instead of vaccines that induced Th2 biased CD4+ T cell responses that aggravate respiratory diseases." (PMID 36759349, 2023). "The induction of CD4+ type 2 helper T-cell (Th2) (IL4, IL5, or IL13) responses has been associated with vaccine-associated enhanced respiratory disease (VAERD), as seen in some patients with respiratory virus infections." (PMID 36685587, 2022). "CoVac-1-induced TH1 CD4+ T cell responses were complemented by multifunctional CD8+ T cells, counteracting the theoretical risk of vaccine-associated enhanced respiratory disease, which has been associated with a TH2-driven immune response." (PMID 34814158, 2022). "The nine immune cells landscape was mapped among those respiratory system diseases, including CD4+ T cells, CD8+ T cells, dendritic cells, B cells, eosinophil, γδT cells, monocytes, neutrophil and natural killer cells." (PMID 34841705, 2021). "Subsequent studies in animal models have implicated roles for CD4 T cells, eosinophils and non-neutralizing antibodies in mediating enhanced respiratory disease." (PMID 25769044, 2015). "Similar patterns were detected in children with recurrent respiratory diseases in the Mogilev and Minsk regions: positive Spearman correlation coefficients were between CD3+/CD4+ T lymphocytes and also between CD3+/CD8+ T lymphocytes, negative coefficients were between CD4+/CD8+ T lymphocytes." (PMID 36294250, 2022). "Depletion of CD4 T cells was shown to significantly reduce inflammatory disease after FI-RSV vaccination of mice prior to challenge, supporting that Th2 CD4 T cells play a critical role in RSV vaccination-enhanced respiratory disease." (PMID 30365561, 2018). "Finally, the occurrence of other respiratory diseases, viral load or circulating CD4 was not different between patients with normal or enhanced rate of FEV1 decline." (PMID 31661533, 2019). "Although the proportion of the total lymphocyte population in camel BALF was not affected by respiratory disease, BALF samples from diseased camels contained higher percentages of CD4+ T cells and B cells, than healthy animals." (PMID 36131278, 2022).
peripheral neuropathy (23 papers, 2009 to 2025). A disorder affecting the peripheral nervous system. "There was also evidence suggesting an association of nadir CD4 cell count at baseline and peripheral neuropathy (p = 0.005)." (PMID 38275937, 2023). "Low CD4+ T-cells <500cells/mm3 is associated with an increased risk of developing peripheral neuropathy and the CD4+ T cells of majority of the participants in this study is low." (PMID 36415339, 2022). "In particular, NOD mice partially deficient in Aire function develop peripheral neuropathy that is mediated by CD4+ T cells targeting myelin P0 and IFN-γ is required for disease to develop, similar to what has been observed in NOD-B7-2KO mice." (PMID 23850635, 2013). "Third, our results show that the pathophysiology of corneal neuropathy has similarities with the pathophysiology of diverse forms of peripheral neuropathy where Th1 CD4+ T cells promote neural damage." (PMID 37217914, 2023). "None of the health status characteristics namely; the level of CD4 cell count, duration of HIV infection and duration on ART, was independently associated with peripheral neuropathy." (PMID 25526665, 2014). "Peripheral neuropathy in NOD-B7-2KO mice is dependent on interferon-gamma (IFN-γ)-producing CD4+ T cells that include autoreactive CD4+ T cells specific for peripheral nerve antigens such as myelin protein zero (P0)." (PMID 23850635, 2013). "At baseline assessment, the median CD4 T-cell count was 263, and 50% patients had evidence of peripheral neuropathy." (PMID 22496970, 2012). "Random forest models (AUC > 0.80) outperformed logistic regression in predicting peripheral neuropathy, with HIV‐1 duration, peak viral load, age and low CD4+ T‐cell count as top predictors." (PMID 40990267, 2025). "Previous studies also reported that after successful therapy neither CD4 count nor viral load suppression decreased the odds of developing peripheral neuropathy." (PMID 30695060, 2019). "Participants had to be eligible for ART, based on the then CD4 eligibility threshold of 350 cells/μL, antiretroviral naïve and have no symptoms of peripheral neuropathy." (PMID 28832288, 2017).
intestinal disease (15 papers, 2011 to 2025). "Our results suggest that production of IL-17 by CD4+ T cells may be a key mediator of IBD in humans, and that loss of Hem1 specifically in CD4+ T cells may contribute to intestinal disease in Hem1-deficient children by secreting IL-17." (PMID 40627451, 2025). "To investigate the role of the T cell infiltrate in the intestinal inflammation observed in P440S mice, we evaluated the effect of CD4+ T cell depletion on intestinal disease." (PMID 37962568, 2024). "Furthermore, the intestinal disease in the LckP440S/P440S mice is prevented by CD4+ T cell depletion or regulatory T cell transfer." (PMID 37962568, 2024). "Thus, our data demonstrates experimentally, that CD4+CD25+ Tregs are capable of modulating Th2 inflammation and fibrosis associated with intestinal disorders." (PMID 21858239, 2011).
inflammatory myopathies (14 papers, 2013 to 2026). "The patient with undefined myopathy mainly presented clones within GZMB+ EM CD4+ T cells which were shared with PB GZMB+ EM T cells." (PMID 37522383, 2023). "Immunohistochemistry revealed type II muscle fiber atrophy with a mixed CD8+ and CD4+ lymphocyte infiltrate, indicative of inflammatory myopathy." (PMID 28716137, 2017). "The main focus of the review is pro-inflammatory CD8+ and CD4+ (Th1, Th2, and Th17) and immunosuppressive regulatory CD4+ (Treg) cells as they relate to muscle physiology; however, B cells and Natural Killer cells have been found in myopathies and post-exercise, respectively." (PMID 33806895, 2021). "In this line, a previous study of inflammatory myopathies in patients evidenced the crucial role of ICOSL in inducing CD4+ T-cell responses (both Th1 and Th2), which could be suppressed in vitro by using an anti-ICOSL antibody." (PMID 28424681, 2017). "The role of CD4+ and CD8+ T-cells in inflammatory myopathies has been recognized; however, their precise roles in the pathogenesis of myositis are not completely understood." (PMID 23758833, 2013). "Histopathology revealed histiocyte-predominant inflammation with myofibre necrosis and regeneration, sparse CD4+ T-cell infiltrates, and absence of fibrosis, consistent with necrotising myopathy." (PMID 42279552, 2026). "However, IL-15 is not only able to attract, but also to generate CD28null T cells, the predominating subset of muscle-resident CD4+ and CD8+ T cells in inflammatory myopathies." (PMID 26646698, 2015). "We found that in a patient suffering from M. Danon and in a patient with polyglucosan body myopathy, accumulation of autophagic vesicles was nearly absent in CD4+ T‐cells, indicating that autophagy is not induced in these cells upon activation in contrast to healthy controls." (PMID 32319705, 2020). "Initial reports have indicated that there are differences in the lymphocyte subsets seen in PM, DM and sIBM; however, recent studies have indicated that those differences are not clear-cut and that T-cells (CD4, CD8), B-cells, macrophages, and DCs are present in all inflammatory myopathies." (PMID 23758833, 2013).